BDNF (brain derived neurotrophic factor)
Diseases named in the same sentence as BDNF in open-access papers (continued):
Sharing a sentence is not in itself a finding about the gene and the disease.
depression (continued). "Currently, there are no reports showing the relationship between α7 nAChR and BDNF–TrkB signaling in depression." (PMID 27821848, 2016). "The impact of potential non-differential misclassification of participants’ depression status in this study is not likely to be related to measured BDNF levels (testing was completed in a blinded manner)." (PMID 25886523, 2015). "The ELISA assay used in our study measured the total of BDNF levels (proBDNF and mature BDNF combined), and thus we were not able to assess possible differences of antepartum depression in the relation with proBDNF and mature BDNF." (PMID 25886523, 2015). "Maternal early pregnancy serum BDNF levels were significantly lower in women with antepartum depression compared to women without depression (mean ± standard deviation [SD]: 20.78 ± 5.97 vs. 21.85 ± 6.42 ng/ml, p = 0.024)." (PMID 25886523, 2015). "Depression-related endophenotypes such as learned helplessness, anhedonia, and vulnerability to stress were not seen in heterozygous BDNF-KO mice." (PMID 25762938, 2015). "Correlation analysis between depression severity and BDNF levels in this group did not reveal any significance." (PMID 26010085, 2015). "The first three showed decreased BDNF during acute mood states, and the last two showed BDNF levels decreased during depression but not in mania." (PMID 26621529, 2015). "Recently more and more attention has been put on the BDNF and MOR and depression." (PMID 25821488, 2015). "A randomized clinical trial was utilized to compare the improvement of depression and brain-derived neurotrophic factor (BDNF) levels between community women with and without music aerobic exercise (MAE) for 12 weeks." (PMID 26075212, 2015). "Though the role of brain derived neurotrophic factor (BDNF) as a marker for major depressive disorder (MDD) and antidepressant efficacy has been widely studied, the role of BDNF in distinct groups of patients remains unclear." (PMID 26010085, 2015). "While related endophenotypes of depression and schizophrenia are seen in various BDNF models, they are not seen simultaneously in the same model." (PMID 25762938, 2015). "Our findings are consistent with most though not all prior studies of BDNF levels and depression among men and non-pregnant women." (PMID 25886523, 2015). "The authors found that loss of BDNF in the DG or CA1 did not affect locomotor activity, contextual memory, cued memory, or baseline anxiety-like, depression-like and hedonic behaviors." (PMID 24817844, 2014). "BDNF(±) mice and other approaches to decrease BDNF signaling have not provided any conclusive evidence regarding the connection between BDNF and depression-like behavior." (PMID 24817844, 2014). "A trend of negative correlation was found between baseline serum BDNF and baseline scores of the 17 items of the Hamilton Rating Scale for Depression (HAMD17) (r = −0.183, p = 0.071)." (PMID 25089150, 2014). "Although a large number of models have been employed and several studies have been published, no clear-cut connections between BDNF levels or signaling and depression-like behavior in mice have emerged." (PMID 24817844, 2014). "More specifically, the interaction between BDNF Val66Met polymorphism and ELS was investigated with regard to brain and arousal pathways to syndromal depression and anxiety in a non-clinical sample." (PMID 24596569, 2014). "While there is little evidence regarding the relevance of COR on CUMS-induced depression, in this study we hypothesized that COR would improve CUMS-induced depression through regulation of r5-HT2A receptor and BDNF." (PMID 25587342, 2014). "Literature data indicate that brain-derived neurotrophic factor (BDNF), cyclic-AMP response element-binding protein (CREB) and phospho-CREB (pCREB) may have a place in depression." (PMID 25431319, 2014). "Taken together, the large number of studies using mice with decreased BDNF expression has not yielded any clear connections between depression and BDNF." (PMID 24817844, 2014).
depression (continued). "The interaction between BDNF and life stress in depression is stronger for stressful life events rather than childhood adversity." (PMID 24433458, 2014). "Other studies examining the role of BDNF in depression have also found that heterozygous knock-out of BDNF did not alter anxiety profile on the elevated-plus maze." (PMID 23847583, 2013). "Unlike BDNF, NGF, and FGF-2, which were reduced in association with depression, plasma levels of VEGF were elevated or unchanged in drug-free patients with an acute episode of major depression and VEGF levels were unrelated to depression scores." (PMID 23675319, 2013). "Serum levels of mature BDNF, but not its precursor proBDNF, are decreased in patients with major depressive disorder." (PMID 23503168, 2013). "BDNF levels were not correlated with any clinical characteristic assessed, but there was a trend for lower BDNF levels in patients with a history of major depression (p = 0.09)." (PMID 23908608, 2013). "In fact, BDNF is sufficient to produce antidepressant behavioral effect; however deletion of BDNF is not enough to induce depression." (PMID 24348327, 2013). "Within the patient group, sexual/ religious symptom content, chronic course of symptoms and the presence of depression or SAD resulted in elevated BDNF levels compared to those without these features." (PMID 23908608, 2013). "Moreover, multiple studies have shown that BDNF is both necessary and sufficient for anti-depressant drug action, which leads to the interesting possibility that BDNF-mediated regulation of Wnt2 expression may be an important mechanistic link in the alleviation of symptoms during depression." (PMID 23639831, 2013). "The level of brain-derived neurotrophic factor (BDNF), a member of the neurotrophin family, is down regulated in Alzheimer’s disease (AD), Parkinson’s disease (PD), depression, stress, and anxiety; conversely the level of this neurotrophin is increased in autism spectrum disorders." (PMID 23320097, 2013). "It has been known for some time that the case for BDNF involvement in depression has not been consistent." (PMID 23824678, 2013). "The mediating role of problem focused coping in the relation between neglect and depression scores was not moderated by BDNF genotype." (PMID 23824678, 2013). "In addition, these cognitive deficits in mice are paralleled by reduced brain-derived neurotrophic factor (BDNF) mRNA expression, in the dentate gyrus and CA3 area of the hippocampus, which is also a marker of depression." (PMID 23675382, 2013). "Decreased serum levels of mature BDNF, but not proBDNF, was found in patients with depressive disorder." (PMID 24040063, 2013). "Some environmental stressors lead to the onset of depression via inhibiting hippocampal BDNF expression, but other environmental stressors-induced depression exhibits no change in BDNF expression." (PMID 23056528, 2012). "Previously, we reported that BDNF serum levels in patients with MDD were significantly lower than those of healthy controls, and that there was a negative correlation between BDNF serum levels and the severity of depression in patients." (PMID 22880079, 2012). "For example, stress-induced increase or no change in BDNF level in animal models of depression was observed in two studies." (PMID 23056528, 2012). "In conclusion, the present study reports that plasma BDNF levels are not different in depressed subjects as compared to controls, and are not related to the severity of depression." (PMID 22768299, 2012). "Depression induced by MD but not CUPS was significantly associated with upregulation of miR-16 and possibly subsequent downregulation of BDNF in hippocampus." (PMID 23056528, 2012). "Examples of gene changes at the intersection of depression and aging were provided (e.g., SST and BDNF), but the exact nature and complexity of changes in multiple genes and pathways and their relevance to disease pathways will be described in details elsewhere." (PMID 23162569, 2012).
depression (continued). "Patients with depressive syndrome who underwent remission had significantly higher plasma BDNF levels (p<0.001), regardless of age or sex." (PMID 22761741, 2012). "Plasma BDNF levels in the non-responder group at the depressive syndrome stage, and at 8 and 12 weeks after the commencement of treatment were 2 932±2 373, 2 117±2 042, and 1 619±1 698 pg/ml, respectively." (PMID 22761741, 2012). "To better understand the role of BDNF in MDD, we compared the changes in plasma BDNF levels in remission and non-responder groups of patients with depressive syndrome." (PMID 22761741, 2012). "Serum BDNF was significantly elevated from weeks 0 to 12 (n = 11, 52.4 ± 16.7 vs. 79.8 ± 13.8, p = 0.001), although it was largely unchanged in the two patients who developed PTSD or major depression during the trial." (PMID 21303552, 2011). "Although not explored to such a great extent as BDNF, the role of other neurotrophins in the pathophysiology of depression is also under investigation." (PMID 22654714, 2011). "Given the fact that depression and AD share common pathophysiological abnormalities of CREB- BDNF signaling pathway, citrus and green tea flavonoids may increase the phosphorylation of CREB and improve the memory." (PMID 20226030, 2010). "Such a serum NGF/BDNF balance is not observed normally nor in psychological stress, depression, autoimmune diseases or acute coronary syndrome." (PMID 21085492, 2010). "Brain-derived neurotrophic factor (BDNF), a member of the neurotrophin family that regulates neuronal plasticity and survival, might explain the connection between depression and the tPA system." (PMID 20300596, 2010). "From the BDNF results it seems that prepubertal WKY rats exhibit lower levels of BDNF in the hippocampus (at least in one region-CA3) as has been found in several human studies and animal studies, and in accordance with the BDNF theory of depression." (PMID 21152205, 2009). "Neurobiologically, depression involves monoaminergic dysregulation, hypothalamic-pituitary-adrenal axis (HPA axis) hyperactivity, neuroinflammation, reduced neurotrophic signaling (e.g., serum brain-derived neurotrophic factor), and altered cortical–subcortical circuit function." (PMID 41586064, 2026). "However, lower BDNF levels are seen in cognitive decline and depression, frequent non-motor symptoms of PD." (PMID 41697575, 2026). "Summarizing, mirtazapine may diminish the negative influence of maternal stress and depression on the offspring brain, via mechanism(s) putatively involving 5-HT neurotransmission and BDNF." (PMID 40855004, 2026). "Regarding biological markers, despite the included studies found a negative correlation between HAM-D scores and BDNF and serotonin levels, there is evidence suggesting that the improvement in depression symptoms is not correlated with BDNF or serotonin levels." (PMID 39985579, 2025). "These inconsistencies suggest that BDNF may not be a reliable marker for depression relief across all individuals or exercise." (PMID 40002745, 2025). "Vitamin D prevented depression-like behavior; BDNF did not change or mediate effect." (PMID 40871684, 2025). "In addition, we found that high dose H2S could improve anxiety and depression-like behavior, mitigate synaptic plasticity deficits, and activate the CREB/BDNF signaling pathway, as well as increase H2S levels in the hippocampus." (PMID 40551819, 2025). "Additionally, these findings allude to other biological factors (e.g., APOE-ε4, cortisol, inflammation, BDNF) being potential mediators for the relationship between depression and cognition that is not directly mediated by the hippocampus." (PMID 39392583, 2025). "Interestingly, levels of brain-derived neurotrophic factor (BDNF) were significantly lower in both the AECOPD group and the depression subgroup, further underscoring the role of this neurotrophic factor in the pathogenesis of depression." (PMID 40823578, 2025).
depression (continued). "Notably, a decrease in BDNF expression in the cortex of CUMS animals was observed, as it has been previously reported in chronic stress animal models and in the PFC of individuals with depression." (PMID 40517150, 2025). "Furthermore, BDNF mRNA expression was decreased in the prefrontal cortex (PFC) of postpartum depression model mice, and injection of BDNF into medial PFC (mPFC) improved depression-like behaviors in the mice." (PMID 40361157, 2025). "However, among men with CP and depression, BDNF levels were significantly lower compared to those without CP, after fully adjusting for the number of depressive symptoms and MCS scores." (PMID 40222813, 2025). "Our findings could add evidence relevant to CUD management by revealing that depression and anxiety symptoms could persist despite pharmacological treatment without influence on BDNF peripheral levels." (PMID 40943216, 2025). "Among individuals without depression, women showed slightly higher serum BDNF levels than men." (PMID 40222813, 2025). "In a CORT-induced depression model, it was found that increasing the expression of ATG5 could lead to overactive neuronal autophagy, which would lead to the significant degradation of BDNF, thus hindering the conversion of NSCs to mature neurons." (PMID 40497971, 2025). "Theseresults suggest that lower serum BDNF levels correlate with depression; theBDNF Val66Met genotype may not significantly influence thisrelationship." (PMID 40352065, 2025). "In the hippocampal CA1 region of depression model mice, FXR overexpression may lead to the cytoplasmic translocation of CREB-regulated transcription coactivator 2 (CRTC2), reducing CREB phosphorylation and activity, which in turn lowers BDNF expression." (PMID 40362260, 2025). "This systematic review revealed the altered expression of miRNAs across multiple depression studies, and the synthesized role of highly frequent miRNAs with altered expressions were enriched in influencing molecules involved in neurobiological processes, such as 5-HT, SERT, and BDNF." (PMID 40598020, 2025). "I3C treatment against chronic social defeat stress (CSDS) showed mitigation of depression-like behavior, but not anxiety-like behavior, which are due to an increase in BDNF levels and inhibition of oxidative stress and inflammation in the hippocampus and prefrontal cortex." (PMID 40094833, 2025). "In addition, smokers in this cohort exhibited significantly lower BDNF levels compared to non-smokers (p = 0.048), supporting the hypothesis that cigarette smoking may contribute to neurotrophic impairment and exacerbate depression risk through suppression of neuroprotective pathways." (PMID 40823578, 2025). "Furthermore, we found that increasing dose of exogenous H2S administration could improve anxiety and depression-like behavior, synaptic plasticity deficits, p-CREB/CREB and BDNF, as well as increase H2S levels in the hippocampus." (PMID 40551819, 2025). "Somatization symptoms may affect the SQ and cognitive function of people with depression, leading to an exacerbation of inflammatory responses; BDNF and ProBDNF levels may be more influenced by the overall state of depression rather than being determined solely by SS." (PMID 40821647, 2025). "Hospital Anxiety and Depression Scale (HADS) scores were analyzed in relation to endothelial function (assessed with flow-mediated dilation), arterial stiffness, and blood biomarkers (fibrinogen, endocan, and brain-derived neurotrophic factor [BDNF]) in post-MI patients." (PMID 40491453, 2025). "In light of the dose–response relationship between total physical activity and various exercise modalities' impact on BDNF levels, and guided by the 2024 Adult Compendium and WHO recommendations for physical activity, we propose preliminary exercise prescriptions for patients with depression." (PMID 40226670, 2024).
depression (continued). "The higher BDNF levels at M0 in patients without DE at M2 could also indicate a difference between good and bad responders to alcohol withdrawal that translates to depression status." (PMID 39430530, 2024). "A previous review reported a negative relationship between blood BDNF and symptom severity in patients with major depression, which is a potential parameter explaining the relationship between cognitive impairment and depression." (PMID 38379321, 2024). "Moreover, BLAN not only potentiates long-term potentiation and long-term depression in the BLA but also results in stress-induced elevation of brain-derived neurotrophic factor (BDNF), mature BDNF, and phosphorylation of tyrosine receptor kinase B expression in the BLA." (PMID 38187456, 2024). "In addition, experiencing too many negative life events in childhood can also change brain-derived neurotrophic factor (BDNF) gene polymorphisms, thus increasing the risk of depression in adulthood." (PMID 39281083, 2024). "Further examination of the dose–response relationship between various exercise interventions and BDNF levels demonstrates that all six exercise modalities (RE, AERE, CAE, Qigong, mindfulness, and yoga) elicit a positive, nonlinear effect on BDNF levels in patients with depression." (PMID 40226670, 2024). "Also, serum BDNF has been reported to depend on the amount and duration of smoking, in smokers with anxiety and/or depression, but without any other reported diseases, it was found that a higher number of smoking years relates to higher serum BDNF." (PMID 39064540, 2024). "The development of depression is hypothesized to stem from disturbances in neurotransmitters, receptors, the hypothalamic-pituitary-adrenal (HPA) axis, cytokines, neuroplasticity, and systemic influences or brain-derived neurotrophic factor (BDNF)." (PMID 39717381, 2024). "Furthermore, alterations in DNA methylation of the brain-derived neurotrophic factor (BDNF) gene, a crucial gene involved in neuroplasticity, have been observed in the pathophysiology of depression, suggesting a potential mechanism for stress-induced mood changes." (PMID 39194576, 2024). "Accordingly, it could be hypothesized that BDNF could be an indicator of depression not related to suicidal actions, and suicide attempts which not go on to complete suicide wouldnot have lower BDNF than depressed patients without suicide attempts." (PMID 39039500, 2024). "Further studies have confirmed that BDNF is released by A2 astrocytes but not by A1 astrocytes, and the reduced BDNF is related to the development of PSD, which is evidenced by the findings that PSD patients have reduced BDNF levels compared with stroke patients without depression." (PMID 38421829, 2024). "However, to date, there has been no study investigating the methylation of BDNF promoter IV among adolescent patients suffering from depression." (PMID 38542252, 2024). "According to a study that assessed plasma brain-derived neurotrophic factor (BDNF) levels before and after BLT in treatment-resistant depression, responders and remitters had higher post-treatment plasma BDNF concentrations than patients who did not achieve response or remission." (PMID 38999491, 2024). "In addition, effective treatments for depression (antidepressant drugs or other non-pharmacological interventions) are able to increase BDNF levels." (PMID 38396487, 2024). "In this study, we revealed the significant differences in serum BDNF, GDNF, 5-HT, and IL-1β among the HC, PWE, and PWECD groups, along with the negative correlation with depression severity in serum GDNF and 5-HT levels, supporting their role in epilepsy and comorbid depression." (PMID 39474368, 2024).